DIABLO (diablo IAP-binding mitochondrial protein)
Description:
Promotes apoptosis by activating caspases in the cytochrome c/Apaf-1/caspase-9 pathway. Acts by opposing the inhibitory activity of inhibitor of apoptosis proteins (IAP). Inhibits the activity of BIRC6/BRUCE by inhibiting its binding to caspases. [Isoform 3]: Attenuates the stability and apoptosis-inhibiting activity of XIAP/BIRC4 by promoting XIAP/BIRC4 ubiquitination and degradation through the ubiquitin-proteasome pathway. Also disrupts XIAP/BIRC4 interacting with processed caspase-9 and promotes caspase-3 activation. [Isoform 1]: Defective in the capacity to down-regulate the XIAP/BIRC4 abundance.
Synonyms: SMAC; DIABLO-S; FLJ25049; FLJ10537; DFNA64
Tractability: PROTAC: UniProt records ubiquitination sites on it; ubiquitination databases record sites on it; its protein half-life has been measured.
Gene: Protein-coding gene on chromosome 12 (122,207,394 to 122,226,062, reverse strand). Ensembl gene ENSG00000184047.
Subcellular location: Mitochondrion; Cytoplasm, cytosol
Subcellular location (Human Protein Atlas): Mitochondria; Cytosol; End piece; Flagellar centriole; Mid piece; Principal piece
Pathways (Reactome):
Programmed Cell Death: Regulation of the apoptosome activity; Release of apoptotic factors from the mitochondria; SMAC (DIABLO) binds to IAPs; SMAC(DIABLO)-mediated dissociation of IAP:caspase complexes; SMAC, XIAP-regulated apoptotic response
Gene Ontology:
Molecular function: protein binding
Biological process: apoptotic signaling pathway; apoptotic process; extrinsic apoptotic signaling pathway via death domain receptors; intrinsic apoptotic signaling pathway; intrinsic apoptotic signaling pathway in response to oxidative stress; neuron apoptotic process; positive regulation of apoptotic process; regulation of apoptotic process; regulation of cell cycle
Cellular component: cytosol; mitochondrion; survivin complex; CD40 receptor complex; cytoplasmic side of plasma membrane; mitochondrial intermembrane space
Genetic constraint (gnomAD): Loss-of-function variants: 30 observed, 32.68 expected, observed/expected ratio (o/e) 0.92, 90% interval 0.69 to 1.25. The upper end of that interval is the gene's LOEUF score, 1.25, which puts it in group 5 of 6, group 1 being the genes least tolerant of losing a copy. Missense variants: 315 observed, 297.25 expected, observed/expected ratio (o/e) 1.06, 90% interval 0.97 to 1.16. Synonymous variants: 132 observed, 108.94 expected, observed/expected ratio (o/e) 1.21, 90% interval 1.05 to 1.4.
Gene-disease validity (ClinGen):
ClinGen rates the evidence that DIABLO causes each of these diseases.
nonsyndromic genetic hearing loss (autosomal dominant): Limited.
Homologues: Orthologues: chimpanzee DIABLO (99% identical), macaque DIABLO (97% identical), dog DIABLO (90% identical), pig DIABLO (89% identical), mouse Diablo (85% identical), rat Diablo (85% identical), rat Diablol1 (85% identical), guinea pig DIABLO (82% identical), rabbit DIABLO (78% identical), tropical clawed frog diablo (54% identical), zebrafish diablob (38% identical), zebrafish diabloa (37% identical).
Diseases named in the same sentence as DIABLO in open-access papers:
DIABLO is named in the same sentence as 53 diseases in open-access papers, as found by Europe PMC text mining. Sharing a sentence is not in itself a finding about the gene and the disease. The quoted sentences say what the papers report.
breast carcinoma (8 papers, 2017 to 2022). "Greenshields and colleagues demonstrated that piperine impacts the intrinsic apoptotic pathway via SMAC/DIABLO regulation in breast cancer cell lines with basal human epidermal growth factor receptor 2 (HER2) expression." (PMID 33256185, 2020). "Furthermore, as in other malignancies, Smac/DIABLO protein was observed to be lowered in breast cancer samples compared to control." (PMID 35406442, 2022).
melanoma (8 papers, 2012 to 2024). A malignant, usually aggressive tumor composed of atypical, neoplastic melanocytes. "However, Smac/DIABLO is able to bind and antagonize the inhibitor of apoptosis proteins (IAP) including survivin, XIAP, c-IAP2, c-IAP1, and livin/melanoma-IAP (ML-IAP) promoting the activation of caspases-3, -7 and -9." (PMID 34093189, 2021). "BCL10 (3.84-fold), TRADD (2.71-fold), CYCS (2.51-fold), DIABLO (2.43-fold), BAD (2.36-fold), BID (2.17-fold), TNFSF8 (2.13-fold), TNFSF10 (2.11-fold), BAX (2.03-fold), and FAS (2.01-fold) were also proapoptotic genes highly upregulated in response to UA treatment in A-375 melanoma cells." (PMID 39473730, 2024).
lung carcinoma (6 papers, 2010 to 2022). "On the contrary, in renal cell carcinoma, lung cancer and hepatocellular carcinoma, DIABLO expression associates with favourable prognostic factors." (PMID 20444257, 2010).
ovarian carcinoma (6 papers, 2012 to 2023). A malignant neoplasm originating from the surface ovarian epithelium. "Previous studies based on the enforced expression of SMAC/DIABLO into ovarian cancer cell lines have provided initial evidences indicating that through this way apoptosis can be induced in ovarian carcinoma without damaging normal ovarian tissue." (PMID 22558117, 2012). "There are studies that reported DIABLO as overexpressed in GC, CRC, and ovarian cancer and as downregulated in PCa, lung, and soft tissue cancers, as well as in BC tissues, with its expression decreasing with BC progression." (PMID 37834160, 2023). "C-IAP2 upmodulation induced by LBW242 in ovarian cancer cells could induce some resistance to apoptosis; however, this inhibition was overcome by the addition of TRAIL to the SMAC/DIABLO inhibitor." (PMID 22558117, 2012).
cervical cancer (5 papers, 2004 to 2022). A primary or metastatic malignant neoplasm involving the cervix. "In general, we observed in HeLa and SiHa cervix cancer cells an up-regulation of some proapoptotic genes after PTX + CIS treatment, including the DIABLO, NOXA, PUMA, CASPASES-3 and -9 genes, which are implicated in the mitochondrial pathway of apoptosis." (PMID 22074157, 2011). "Since both XIAP and survivin are overexpressed in cervical cancer, the level of Smac/DIABLO expression should depend not only on mRNA expression, but also on the balance between these proteins and the release from mitochondria." (PMID 17067390, 2006).
neuroblastoma (5 papers, 2010 to 2025). Neuroblastoma (NB) is the most common solid, extracranial childhood tumor. "DIABLO mRNA expression was exceptionally high in neuroblastoma but the protein was only detected in the mitochondria." (PMID 22788920, 2012). "DIABLO mRNA expression levels in neuroblastoma tumors are surprisingly high compared to other types of tumors and compared to normal tissue." (PMID 22788920, 2012). "Using the in silico data mining approach, we identified elevated expression of five genes located at the 12q24.31 amplicon in neuroblastoma (DIABLO, ZCCHC8, RSRC2, KNTC1 and MPHOSPH9)." (PMID 20444257, 2010). "Among these, DIABLO showed the strongest and most specific activation in a subset of neuroblastoma samples." (PMID 20444257, 2010). "Even though the exact role of DIABLO in neuroblastoma remains to be elucidated, previous contradictory results suggest that DIABLO has both a direct and inverse correlation to prognosis in various cancers." (PMID 20444257, 2010). "In this sense, the carcinogenetic role of DIABLO is ambiguous, and needs to be examined more thoroughly, also in neuroblastoma." (PMID 20444257, 2010). "Among these, DIABLO showed the strongest activation suggesting a putative role in neuroblastoma progression." (PMID 20444257, 2010). "We therefore investigated whether the high BIRC6 expression allows neuroblastoma cells to survive the high levels of the pro-apoptotic protein DIABLO." (PMID 22788920, 2012). "These experiments suggest that BIRC6 may effectively inactivate cytoplasmic DIABLO in neuroblastoma cells and can thereby prevent an apoptotic response." (PMID 22788920, 2012). "To test this hypothesis, we first investigated by a co-immunoprecipitation analysis whether BIRC6 and DIABLO physically interact in neuroblastoma cells." (PMID 22788920, 2012). "To test whether DIABLO can be functionally activated upon an apoptotic stimulus, we treated neuroblastoma cells with the BCL2 inhibitor ABT263, which results in stimulation of pore formation in the mitochondria." (PMID 22788920, 2012). "Furthermore, results of in silico data mining suggest a new neuroblastoma target gene, DIABLO, within this region, whose functional and therapeutic role remains to be elucidated in follow-up studies." (PMID 20444257, 2010). "In addition to confirming previously identified oncogenes in neuroblastoma, our analysis led to the identification of 12q24.31 gain as a novel marker in neuroblastoma progression, as well as upregulation of DIABLO specifically in a subset of neuroblastoma samples within this region." (PMID 20444257, 2010). "Betulinic acid has also been reported to work efficiently with doxorubicin and potentiate the release of SMAC/DIABLO and cytochrome c from mitochondria in neuroblastoma cells." (PMID 36615262, 2022). "Betulinic acid and TRAIL synergistically triggered the release of SMAC/DIABLO and cytochrome c from mitochondria in SHEP neuroblastoma cells." (PMID 36615262, 2022). "Co-immunoprecipitation confirmed direct interaction between DIABLO and BIRC6 in neuroblastoma cell lines." (PMID 22788920, 2012).
prostate carcinoma (3 papers, 2014 to 2022). A carcinoma that arises from epithelial cells of the prostate gland. "Treatment with Trichostatin A can activate caspase-9 and release mitochondrial cytochrome c and diablo, IAP-binding mitochondrial protein (DIABLO; Smac) in TRAIL resistant prostate cancer cells." (PMID 24739220, 2014).
renal cell carcinoma (3 papers, 2004 to 2010). "Studies have reported that the balance between XIAP and Smac/DIABLO expression is gradually disturbed during progression of renal cell carcinomas and testicular germ cell tumors." (PMID 19397802, 2009).
gastric cancer (2 papers, 2010 to 2022). A primary or metastatic malignant neoplasm involving the stomach. "In cervical and gastric cancer, DIABLO activation has been shown to associate with unfavourable prognostic parameters." (PMID 20444257, 2010).
thyroid cancer (2 papers, 2020 to 2023). "Overall, these results suggest that SMAC/DIABLO is a mediator of TUSC2 biological effects in thyroid cancer cells." (PMID 31973107, 2020). "Additionally, TUSC2 was found to induce thyroid cancer cell apoptosis via intrinsic apoptosis factors SMAC/DIABLO and cytochrome C upregulation." (PMID 37173921, 2023). "Interestingly it has been demonstrated that, in thyroid cancer cells, resistance to chemotherapeutic agents requires low levels of SMAC/DIABLO." (PMID 31973107, 2020). "To further gain insight into the molecular mechanisms induced by TUSC2 in thyroid cancer cells, we focused on the role of SMAC/DIABLO." (PMID 31973107, 2020). "Thyroid cancer cell lines overexpressing TUSC2 demonstrate a significant increase in SMAC/DIABLO and cytochrome C expression following treatment with an apoptosis inducer, suggesting that TUSC2 sensitizes thyroid cancer cells to apoptosis via upregulation of SMAC/DIABLO and cytochrome C." (PMID 37173921, 2023).
adenoma (1 paper, 2017). A neoplasm arising from the epithelium. "The mRNA expression of livin, its isoforms α and β, XIAP, CASP3 and DIABLO was evaluated by qRT-PCR in 82 fresh-frozen adrenal tissues (34 ACC, 25 adenomas = ACA, 23 normal adrenal glands = NAG)." (PMID 28030838, 2017).
adrenocortical tumors (1 paper, 2017). "DIABLO mRNA levels were similar between NAG (0.245 ± 0.179) and adrenocortical tumors (0.241 ± 0.204 and 0.232 ± 0.189, respectively in ACC and ACA)." (PMID 28030838, 2017).
cardiac ischemia (1 paper, 2023). "Additionally, the expression of DIABLO was associated with cardiomyocyte apoptosis, which is induced by cardiac ischemia." (PMID 37476628, 2023).
Down syndrome (1 paper, 2025). "Other alterations included compound GJB2/GJB6 mutations, DIABLO gene variants, and Down syndrome (n = 2 each, 2.4%)." (PMID 41303275, 2025).
ischemia (1 paper, 2015). A hypoperfusion of the BLOOD through an organ or tissue caused by a PATHOLOGIC CONSTRICTION or obstruction of its BLOOD VESSELS, or an absence of BLOOD CIRCULATION. "In addition, interaction of XIAP with Smac/DIABLO has been demonstrated to mediate apoptosis following diverse insults, including ischemia, oxidative stress and ultraviolet radiation." (PMID 25394481, 2015).
ischemic stroke (1 paper, 2024). A stroke disorder caused by obstruction of blood flow to the brain, due to thrombotic (local blood clot formation) or embolic (due to a blood clot or other material traveling from another site) event. "Smac/DIABLO released from the mitochondria can neutralize the protective effects of XIAP and subsequently promote caspase-3-mediated apoptosis after ischemic stroke." (PMID 38645497, 2024).
liver disorder (1 paper, 2023). A disease involving the liver. "DIABLO can promote liver cell apoptosis in liver disorders, including in NADH progression." (PMID 37859957, 2023).
cancer (53 papers, 2009 to 2025). A tumor composed of atypical neoplastic, often pleomorphic cells that invade other tissues. "DIABLO has been reported to have proapoptotic effects in cells and therefore overexpression of DIABLO is believed to cause antitumoral activity via cancer cell sensitization to apoptotic cell death." (PMID 20444257, 2010). "Particularly, an increase of proteins involved in redox balance, antioxidant defenses (CS, NDUFAF7, UQCRC2) and mitochondrial morphology (IMMT) was observed while cancer promotion proteins (DIABLO, TCPT) decreased." (PMID 33801925, 2021). "Several studies have shown that overexpression of SMAC/DIABLO can sensitize cancer cells to apoptosis, thus the development of small-molecule SMAC mimetics has been an attractive goal for cancer treatment in the last decade." (PMID 31973107, 2020). "Livin is over-expressed in several cancer types and presents an anti-apoptotic activity mediated mostly by the direct inhibition of caspase 3, but also of caspases 7 and 9 and DIABLO." (PMID 28030838, 2017). "Small molecules that mimic the IAP-binding motif of second mitochondrial activator of caspases (SMAC, also known as DIABLO), the endogenous IAP antagonist, named SMAC mimetics, have recently been developed and are being tested in human clinical cancer trials." (PMID 24633224, 2014). "Although the alterations of SMAC/DIABLO occurred in 95 samples out of 10,950 patients with cancer (0.9%), this still might be a potential mechanism of SMAC dysfunction." (PMID 32325691, 2020). "Antineoplastic mimics of the second mitochondria-derived activator of caspases (Smac, also called the direct inhibitor of apoptosis-binding protein with low pI, DIABLO) have been used to sensitize cancer cells to apoptosis by targeting inhibitors of apoptosis proteins (IAPs,)." (PMID 31635379, 2019). "Of these DEGs, 6 (EGFR, GATA3, DIABLO, CFLAR, RIPK3, and MAPK8) were repressed, while (ZBP1, PLK1, SPATA2, BCL2, ALK, FASLG, TNFRSF21, and LEF1) were upregulated in cancer cases." (PMID 35610275, 2022). "In accordance with the tumor suppression function of TUSC2 in other cancers, in a subsequent paper, it was shown that in TC, this gene hindered cell proliferation and motility and increased sensitivity to apoptosis by stimulating SMAC/DIABLO and CYTOCHROME C proteins." (PMID 39000555, 2024).
tumor (35 papers, 2004 to 2025). "The expression of DIABLO inversely correlates with the BC tumor stage, suggesting that this protein may play an important role in BC development." (PMID 37834160, 2023). "The ability of Smac/DIABLO agonists to enhance the apoptosis-inducing potential of chemotherapeutic drugs and irradiation, and sensitize TRAIL-resistant tumor cells suggests that Smac/DIABLO may induce fundamental alterations in cell signaling pathways." (PMID 18590557, 2008). "Furthermore, Smac/DIABLO agonists sensitized various tumor cells in vitro and in vivo for apoptosis induced by death-receptor ligation or cytotoxic drugs." (PMID 18590557, 2008). "Therefore, low level of Smac/DIABLO in the serum may be a novel mechanism of tumor cells’ escape from apoptosis in muscle-invasive bladder cancer." (PMID 22218530, 2012). "The results show that BRAF, CDKN1A, DIABLO, PEA15, ERRFI1, and RPS6KB1 are highly expressed in tumor cell lines, which is the same as in the TCGA database." (PMID 39239554, 2024). "Several genes were found at lower expression levels in tumor cases, such as AXL, BAHC2, CFLAR, and DNMT1 while others were overexpressed such as BNIP3, DIABLO, FADD, and IDH1." (PMID 35911707, 2022). "DIABLO is the major antagonist of IAP proteins, sensitizes tumor cells to apoptosis and controls the tumor growth and/or its metastatic spread." (PMID 28030838, 2017). "However, DIABLO was recently found to be involved in non-apoptotic processes that are essential for tumor growth and progression, such as phospholipid synthesis associated with tumorigenesis." (PMID 37834160, 2023).
DIABLO also shares sentences with these, for which no sentence is quoted: infection (3 papers); colorectal cancer (2); esophageal cancer (2); glioma (2); hepatocellular carcinoma (2); myeloma (2); pancreatic cancer (2); autoimmune disease (1); autosomal-dominant nonsyndromic hearing loss 64 (1); bacterial infection (1); bladder cancer (1); Cerebral ischemia (1); chronic myeloid leukaemia (1); depression (1); gastric adenocarcinoma (1); gout (1); gynecological tumors (1); HCMV infection (1); hearing loss (1); leukemia (1); liver cancer (1); lymphoid leukaemia (1); medulloblastoma (1); myeloid leukaemia (1); myeloid malignancies (1); non-small cell lung carcinoma (1); oral cancer (1); rheumatoid arthritis (1); sarcoma (1); Sepsis (1).
A further 4 diseases each share a sentence with DIABLO in 1 paper.